IL10 (interleukin 10)
Diseases named in the same sentence as IL10 in open-access papers (continued):
Sharing a sentence is not in itself a finding about the gene and the disease.
cancer (continued). "It has been reported that IL-10 gene polymorphism plays an important role in the occurrence and development of cancers such as BC, gastric cancer, lung cancer." (PMID 35186043, 2022). "Marked increase in IL-6 and IL-10 levels subsequent to PTX administration in cancer patients have been reported to be associated with joint pain and fatigue." (PMID 35273508, 2022). "Prior studies indicate that IL-4 and IL-10 polarize IgG4 class switching, and that IgG4 + B cells are increased in advanced cancer, and associate with poor patient survival and increased recurrence." (PMID 35255925, 2022). "It is worth mentioning that CXCR3, CCR7, and IL10 have been reported to be the underlying mechanisms in cancer metastasis-induced BCP in human." (PMID 34025351, 2021). "For example, cancer cells produce an overabundance of IL6 or IL10, which is associated with poor prognosis." (PMID 34512714, 2021). "Conversely, a meta-analysis of serum IL-10 in 1788 cancer patients showed that high seurm IL-10 levels were significantly associated with worse OS and disease-free survival (DFS) at 1 year, 3 years, and 5 years for both solid and hematological malignancies." (PMID 34768810, 2021). "In parallel with studies in mouse models, IL-10+ B cell numbers have also been associated with human cancer progression." (PMID 34359321, 2021). "As an immunosuppressive cytokine, high serum concentration of IL-10 is associated with advanced stage and poor prognoses of cancer." (PMID 34625124, 2021). "For instance, inactivation of FOXO3 is associated with the initiation and progression of cancer and has a role in infectious diseases through regulation of IL-10." (PMID 35047509, 2021). "Observational studies in humans as well as reports in animal models have separately shown that age, pregnancy, and cancer were associated with changes in IL-10 and in myeloid cells." (PMID 33878120, 2021). "Bregs can affect multiple immune cells, including T cells, through the secretion of anti-inflammatory cytokines, such as TGF-β and IL-10, causing inhibited anti-cancer responses." (PMID 33808959, 2021). "IL-10, an anti-inflammatory cytokine, protects the body from damage caused by immune overreaction, while IL-10 in cancer has two opposite effects." (PMID 34712741, 2021). "For example, apoptotic cancer cells release immunosuppressive factors, such as transforming growth factor-β, interleukin-10 (IL-10), and sphingosine-1-phosphate, causing repolarization of M1 to M2 macrophages." (PMID 33298099, 2020). "It had been reported previously that MerTK- or PROS1-deficient mice display lower levels of IL-10 production by myeloid cells following bacterial or viral activation, or in cancer models." (PMID 33101282, 2020). "For example, IL-10 not only down-regulates HLA-I but also up-regulates HLA-G, and causes immune escape in cancer cells." (PMID 32547401, 2020). "This premise is supported by our previous work illustrating that Hh infection induced more invasive cancer in the lower bowel of Rag2-deficient male mice receiving Il10-deficient regulatory T cells compared to their female counterparts." (PMID 33255175, 2020). "Differences in the cytokine profile showed that IL-2 and IL-10 present a near-significant association with the cancer relapse." (PMID 32013102, 2020). "Elevated serum levels of IL10 observed in prostate and other cancer patients are associated with poor prognosis." (PMID 32802517, 2020). "It is important to note that the role of IL-10 in cancer immunotherapy is nuanced, with IL-10 being associated with detrimental and beneficial effects dependent on context." (PMID 30728070, 2019). "In our previous studies of the TMEs of several different cancer types, we found that elevated levels of transcripts for the cytokines IL-1a, IL-10, IL-27 and IL-32 g, in addition to IFN-g, were associated with PD-L1 protein expression." (PMID 31730010, 2019).
cancer (continued). "Elevated IL-10 in cancer is associated with TAM infiltration, downregulating pro-inflammatory cytokines, MHC class II molecules, and co-stimulatory proteins." (PMID 31769418, 2019). "Pro-inflammatory cytokines IL-2, IL-12 and IFN-γ are associated with good prognosis in cancer, whilst an increase of immunosuppressive cytokines IL-6, IL-10 and TGF-β correlates to poor outcome." (PMID 30232514, 2019). "IL-10 was associated with increased risk of cancer mortality when log-transformed (HR: 1.77, 95% CI: 1.26–2.48) and comparing 3rd vs. 1st tertile (HR: 3.06, 95% CI: 1.35–6.89) in fully adjusted models." (PMID 31448052, 2019). "The prominence of cancer risk related to IL-10 alleles and its protein expression is not fully understood and varies among different types of cancers." (PMID 31769418, 2019). "Infiltration of TAMs was shown to be associated with poor survival in cancer patients, as a consequence of the overexpression of CSF-1 and immunosuppressive cytokines such as IL-4 and IL-10 in the TME." (PMID 30987642, 2019). "IL-6 and IL-10 are two other growth factors released by cancer cells able to induce immune system deficiencies." (PMID 30477198, 2018). "Recent reports suggested that most of the pro-inflammatory cytokines, including IL-2, IL-6, IL-1β and IL-10, are over-expressed at cancer specific sites and particularly linked to invasion and progression of sever HCC conditions." (PMID 29651140, 2018). "IL-10 is an immunosuppressive and anti-inflammatory cytokine linked with inflammation-associated cancer." (PMID 30112116, 2018). "This was an unexpected finding since production of IL-10 is an immunosuppressive cytokine that has been implicated in cancer-associated immunodysfunction." (PMID 29606140, 2018). "A significant association was found between IL-10 -592A/C polymorphism and increased overall cancer risk (homozygous: OR = 1.13, 95% CI = 1.00-1.28, P = 0.001)." (PMID 28977953, 2017). "Multiple meta-analyses were conducted to investigate the association between IL-10 rs1800896 polymorphism and cancer risk." (PMID 29029504, 2017). "In the Chinese population, numerous case-control studies were performed to investigate the role of IL-10 -1082A/G, -819T/C and -592A/C polymorphisms in cancer risk." (PMID 28977953, 2017). "Numerous studies have examined the associations of three promoter polymorphisms (-1082A/G, -819T/C and -592A/C) in IL-10 gene with cancer susceptibility in the Chinese population, but the results remain inconclusive." (PMID 28977953, 2017). "Three meta-analyses including international studies have investigated the association of IL-10 -1082A/G, -819T/C and -592A/C polymorphisms with overall cancer susceptibility." (PMID 28977953, 2017). "Pooled results indicated that the three promoter polymorphisms in IL-10 gene were significantly associated with an increased overall cancer risk in the Chinese population." (PMID 28977953, 2017). "In this meta-analysis, we comprehensively investigated the associations between three promoter variants (-1082A/G, -819T/C and -592A/C) in IL-10 gene and cancer risk in the Chinese population through 53 articles." (PMID 28977953, 2017). "A significant association was found between IL-10 -1082A/G polymorphism and overall cancer risk [dominant: odds ratio (OR) = 1.32, 95% confidence interval (CI) = 1.04-1.67, P < 0.001]." (PMID 28977953, 2017). "First, it identified the significant association between IL-10 -1082A/G, -819T/C and -592A/C polymorphisms and an increased overall cancer risk in the Chinese population." (PMID 28977953, 2017). "The results revealed that all the three IL-10 gene polymorphisms we considered were associated with an increased overall cancer risk." (PMID 28977953, 2017). "It has been shown that circulating concentrations of IL-10 were raised in 13 different cancer types and were associated with adverse disease stage or with negative prognosis." (PMID 28234961, 2017).
cancer (continued). "Other meta-analyses with international studies have assessed the association between polymorphisms in IL-10 gene and susceptibility to some types of cancer." (PMID 28977953, 2017). "Although this association needs further confirmation by considering large studies, this meta-analysis suggested an association between IL-10 gene polymorphisms and cancer risk in the Chinese population." (PMID 28977953, 2017). "IL-10 signaling plays a key role in regulation of cancer-associated inflammation including regulation of CD8 T cells." (PMID 26747525, 2016). "In their research higher concentrations of IL-10 were associated with more severe disease and poorer prognosis of cancer." (PMID 27547238, 2016). "As a result, certain polymorphisms located in the promoter region of IL-10 gene (−592C>A, −819C>T and −1082A>G), which regulate the expression level of IL-10 protein, were thought to be implicated in the pathogenesis of various kinds of cancers." (PMID 27995011, 2016). "At this time, a series of seven molecular epidemiological studies and meta-analyses have investigated the association between the IL-10 -819 SNP, a transition (C → T) and the susceptibility to different cancer types among different populations." (PMID 27220278, 2016). "Genotype–phenotype association was based on 10 studies with circulating IL-10 level measured in cancer patients or healthy controls." (PMID 26886630, 2016). "Previous studies have suggested that the increase in IL-10 can track inflammatory responses and cancer development and constitute a risk factor for carcinogenesis." (PMID 26905729, 2016). "The IL-10 -1082 SNP rs1800896 is a transition (A → G) and is the most extensively studied polymorphism in the IL-10 gene in cancer susceptibility." (PMID 27220278, 2016). "Interleukin-24(IL-24), also referred to as melanoma differentiation-associated gene-7(mda-7), is a unique member of the IL-10 gene family, which displays nearly ubiquitous cancer-specific toxicity." (PMID 26361755, 2015). "Here we meta-analyzed the published data about the expression of IL–10 in serum of 1788 cancer patients from 21 published studies and their association with survival for studies that evaluated IL–10 by ELISA." (PMID 26440936, 2015). "In the stratified analysis by cancer types, IL–10 overexpression was associated with worse 1-year OS in solid tumors (OR = 4.00, 95% CI = 2.88 to 5.55, P < 0.0001)." (PMID 26440936, 2015). "IL–10 overexpression was also associated with worse 3-year OS in cancer patients (OR = 3.33, 95% CI = 2.53 to 4.39, P < 0.0001)." (PMID 26440936, 2015). "We searched PubMed and EBSCO for studies in evaluating the association of IL–10 expression—in serum and clinical outcome in cancer patients." (PMID 26440936, 2015). "The result was similar to that of 1-year and 3-year, IL–10 overexpression was significantly associated with worse 5-year OS of cancer (OR = 2.80, 95% CI = 1.90 to 4.10, P < 0.0001)." (PMID 26440936, 2015). "Functional IL10 polymorphisms are of particular interest when describing BC because IL-10 has both potentially cancer-promoting immunosuppressive and potentially cancer-inhibiting antiangiogenic properties." (PMID 26112140, 2015). "Results showed that IL–10 overexpression was associated with worse 1-year OS in cancer patients (OR = 3.70, 95% CI = 2.81 to 4.87, P < 0.00001)." (PMID 26440936, 2015). "The ability of TREG to decrease risk for cancer and counteract established tumors depends upon microbe-triggered IL-10, which works to maintain immune system homeostasis and reinforce a protective anti-inflammatory, anti-neoplastic TREG phenotype." (PMID 24778636, 2014). "HLA-G expression is induced following IL-10 stimulation in experiments in vitro and is associated with IL-10 expression in vivo in a context of cancer." (PMID 24839609, 2014). "This allowed us to investigate the effect of clinically observed cancer mutations on our IL-10 centered network." (PMID 25056661, 2014).
cancer (continued). "IL-10 is overexpressed in a series of human cancers, which is associated with advanced stage and bad prognosis." (PMID 24585413, 2014). "IL-10 polymorphisms have been widely studied and are reported to be associated with certain other cancers and diseases; however, to the best of our knowledge, this is the first analysis of IL-10 polymorphisms and plasma IL-10 levels in patients with LSCC." (PMID 24765208, 2014). "In line with suppression of the NF-κB pathway, we observed a concentration-dependent downregulation of the inflammatory and regulatory mediators TNF-α, IL10 and NO being implicated in development and progression of various cancers." (PMID 25271635, 2014). "In previous years, several studies have indicated that the IL-10 promoter polymorphisms are associated with an increased risk of cancers, including lung, thyroid, prostate, cervical and gastric cancers." (PMID 24765208, 2014). "This allowed us to enrich the structural interaction data of IL-10 with its partners, and to analyze the mechanisms of mutations that lead to inflammation, and cancer through their impact on predicted interactions." (PMID 25056661, 2014). "To date, a number of case–control studies were conducted to detect the association between IL-10-592C>A polymorphism and cancer risk in humans." (PMID 23460834, 2013). "To date, a number of case-control studies were conducted to investigate the association between IL-10 -592 C>A and cancer risk in humans." (PMID 23460834, 2013). "So, we performed the present meta-analysis to evaluate the association between IL-10 -592 C>A and cancer risk." (PMID 23460834, 2013). "Where cytotoxic cancer therapies result in cancer cell death via apoptosis, interaction, with apoptotic cells cause macrophages to secrete classic M2, anti-inflammatory cytokines, including IL-10 and TGFβ." (PMID 23653658, 2013). "Consistently, we also found that individuals with the AA genotype which exhibits low production of IL-10 were associated with a lower cancer risk than participants with the CC genotype in our meta-analysis." (PMID 23460834, 2013). "In conclusion, our meta-analysis suggests that the IL-10-592C>A polymorphism was associated with a significant decrease in overall cancer risk, especially in smoking-related cancer, Asians and hospital-based studies." (PMID 23460834, 2013). "Additional studies are warranted to further validate ethnic difference in the effect of the IL-10-592C>A polymorphism on cancer risk, especially in Africans." (PMID 23460834, 2013). "The results provided evidence that the IL-10-592C>A polymorphism was associated with a significant decrease in overall cancer risk." (PMID 23460834, 2013). "We previously showed the effects of the cancer-associated suppressive cytokine IL-10 on the phenotype and allogeneic T cell priming ability of human skin-emigrated DC." (PMID 23875023, 2013). "The present meta-analysis investigated the association between the IL-10-592C>A polymorphisms and cancer risk, based on 70 published case–control studies from 65 articles." (PMID 23460834, 2013). "The development of HPV-infected cancer has been shown to be associated with interleukin-10 (IL-10) expression." (PMID 23118878, 2012). "Mice deficient in IL-10 genetically (IL-10−/−) or functionally via antibody neutralization can also develop enhanced antibladder cancer immunity in response to intravesical BCG." (PMID 21941579, 2011). "In this study, we address the importance of the polymorphisms IL–6 GC–174, IL–10 G–1082, C–819, C– 592, which are known to affect the transcription levels of the genes and are also known to be important for cancer cell growth." (PMID 22567049, 2011). "Multiple epidemiological studies have investigated the association between the IL-10 polymorphisms and the risk of different cancer types." (PMID 20735825, 2010). "IL-10 suppression could counteract tumor-associated immunosuppression, while Ca2+ channel-targeting toxins may disrupt cancer cell signaling." (PMID 41155199, 2025).
cancer (continued). "The combination of IL-6 <185 pg/mL and IL-10 <20 pg/mL identified low-risk patients with a septic shock rate of only 0.7%, suggesting these cytokines enable early risk stratification in febrile pediatric cancer patients." (PMID 40647525, 2025). "Elevated levels of IL-10 may reduce bacterial immune clearance and increase cancer risk in chronic H. pylori gastritis." (PMID 41376630, 2025). "In some cancers, elevated IL-10 levels are associated with a worse prognosis, as it may limit the antitumor immune response." (PMID 41379186, 2025). "Unique CAMs-M2 interact with CRC cells via integrin-associated protein (IAP)/SIRPα signaling, promoting cancer cell growth and migration through the release of IL-4, IL-8, IL-10, and cysteinyl leukotriene D4 (LTD4), and increased IL-10 levels further enhance the function of CAMs-M2." (PMID 39125923, 2024). "On the other hand, high expression of serous IL–10 could lead to an adverse survival in most types of cancer and was related to the risk of immune-related adverse events." (PMID 39502692, 2024). "Given IL-10’s well-documented anti-inflammatory properties, its deficiency can lead to heightened inflammatory responses, potentially resulting in poor prognosis in cancer patients." (PMID 39684475, 2024). "Additionally, LAMs induced by FAP+ cancer-associated fibroblasts inhibited T-cell proliferation and effector functions by secreting Granzyme-B and IL-10." (PMID 38303024, 2024). "In cancer pain, key ILs implicated include IL-1, IL-6, IL-10, IL-17, IL-18, and IL-33." (PMID 38940936, 2024). "Additionally, we found that IL-10 was negatively associated with esophageal tumorigenesis, suggesting its potential protective role against cancer development." (PMID 39496002, 2024). "Collectively, these data provide evidence that cancer type-specific TME-associated factors govern the ability of IL-10 to act as either a pro- or an anti-tumoral cytokine, and highlight the need for further studies to clarify the functions of IL-10 in specific pathological contexts." (PMID 39281678, 2024). "Breg cells affect immune cells such as T cells and NK cells or cancer-associated fibroblasts (CAFs) by secreting anti-inflammatory IL-10, IL-35, and TGF-β or by expressing cell-membrane bound immune-checkpoint molecules, including PD-1, PD-L1, and granzyme B (GrB) in solid tumors." (PMID 37033931, 2023). "As shown in in vivo studies, mutations in IL-10 or IL-10R signalling underlie disturbances in intestinal integrity and homeostasis, which can lead to severe forms of IBD in humans, and dysregulated IL-10 function has also been associated with cancer and chronic inflammation." (PMID 36835169, 2023). "IL-10 gene is located on chromosome 1 (1q31-1q32), and SNPs in its promoter region, -1082 A/G, can alter its expression and therefore can lead to alterations in cancer susceptibility and cancer progression." (PMID 37501757, 2023). "However, the subgroup analysis by cancer type revealed positive results, indicating that the IL-10 rs1800896 gene polymorphism was a risk factor for oral SCC." (PMID 37077342, 2023). "Both preclinical and clinical data supported that the IL-18 induction was a functionally relevant biomarker associated with the IL-10 treatment for cancer and hence it was used as a common PD endpoint that connects mice to monkeys for the efficacious dose projection." (PMID 35795558, 2022).